SLC7A11 (solute carrier family 7 member 11)
Diseases named in the same sentence as SLC7A11 in open-access papers (continued):
Sharing a sentence is not in itself a finding about the gene and the disease.
lung adenocarcinoma (57 papers, 2021 to 2026). A carcinoma that arises from the lung and is characterized by the presence of malignant glandular epithelial cells. "SLC7A11 was discovered among the 16 mRNAs associated with overall survival in lung adenocarcinoma patients." (PMID 39944353, 2024). "Lung adenocarcinoma cells harboring KRAS mutations exhibit sensitivity to ferroptosis induced by SLC7A11 inhibitors." (PMID 38314086, 2024). "KRAS-mutant lung adenocarcinoma cells are susceptible to SLC7A11 inhibitor-induced cell death, resulting in attenuated tumor growth in vivo." (PMID 37161053, 2023). "Overexpression of SLC7A11 in KRAS-mutant lung adenocarcinoma (LUAD) patients is linked to increased susceptibility to SLC7A11 inhibition in cells carrying KRAS-mutant LUAD, which significantly reduces cystine uptake and intracellular glutathione biosynthesis." (PMID 37845218, 2023). "Suppressing the SLC7A11/glutathione axis resulted in synthetic lethality in lung adenocarcinoma with mutated KRAS." (PMID 34531924, 2021). "Inhibition of SLC7A11 leads to poor prognosis in KRAS-mutated lung adenocarcinoma." (PMID 34630529, 2021). "It is shown that SLC7A11 is overexpressed in patients with KRAS-mutant lung adenocarcinoma and has a positive correlation with tumor progression." (PMID 39569390, 2025). "Recently, identified as a novel biomarker for early diagnosis of lung adenocarcinoma, circP4HB protects lung adenocarcinoma from iron death by regulating miR-1184/SLC7A11 axis-mediated glutathione synthesis." (PMID 40028033, 2025). "We found that SLC7A11 expression was obviously increased in lung adenocarcinoma (LUAD) tissues when compared with that in normal tissues." (PMID 38561419, 2024). "In KRAS-mutant lung adenocarcinoma, the inhibition of SLC7A11 reduces tumorigenesis, demonstrating its role in ferroptosis evasion under oxidative stress." (PMID 38539554, 2024). "For example, the enrichment of METTL3 in lung adenocarcinoma activated a decrease in SLC7A11 m6A levels, which in turn impeded cell ferroptosis and accelerated tumor progression." (PMID 38221933, 2024). "In another study, uc.339 promotes the development and metastasis of lung adenocarcinoma in vivo by regulating the uc.339/miR-339/SLC7A11 axis, where the inhibition of miR-339 leads to increased expression of SLC7A11 and weakens ferroptosis." (PMID 37036543, 2023). "METTL3 can mediate m6A modification of SLC7A11 mRNA, which stabilizes SLC7A11 mRNA and promotes its translation, thus enhancing ferroptosis resistance of lung adenocarcinoma and hepatoblastoma." (PMID 37714846, 2023). "LncRNAs often acted as a sponge of miRNA to promote SLC7A11 expression at mRNA and protein levels, such as lncRNA UC.339 / miR-339 /SLC7A11 axis promoted lung adenocarcinoma proliferation, migration and invasion by inhibiting ferroptosis." (PMID 37127605, 2023). "The expression of circP4HB in lung adenocarcinoma (LUAD) was found to be elevated both in vivo and in vitro, and it was shown to prevent ferroptosis caused by erastin through regulating miR-1184/SLC7A11-mediated GSH production, which promoted tumor growth." (PMID 37480146, 2023). "HG106, recently known as a potent SLC7A11 inhibitor, also showed marked tumor suppression and prolonged survival in the preclinical mouse models of KRAS-mutated lung adenocarcinoma." (PMID 36552652, 2022). "The lncRNA Uc.339 inhibited the production of mature miR-339 and regulated SLC7A11, leading to defects in ferroptosis and driving the metastasis of lung adenocarcinoma." (PMID 35804831, 2022). "The imbalance of miR-339 led to the up-regulation of the ferroptosis-related gene SLC7A11 and the reduction of ferroptosis levels, which promotes the metastasis of lung adenocarcinoma." (PMID 35399708, 2022). "YTDHC2 promoted the decay of SLC7A11 in an m6A-dependent manner and consequently suppressed the tumorigenesis of lung adenocarcinoma by targeting SLC7A11-mediated antioxidant function." (PMID 35164788, 2022).
lung adenocarcinoma (continued). "Compared with normal subjects, the expression of SLC7A11 in patients with lung adenocarcinoma is significantly increased." (PMID 35399708, 2022). "Treatment with anti-SLC7A11 siRNAs induces significant cell death in KRAS-mutant lung adenocarcinoma cells." (PMID 35280777, 2022). "The histone deacetylase inhibitor vorinostat promotes ferroptosis in EGFR-mutant lung adenocarcinoma cells by inhibiting SLC7A11 (xCT) and enhancing the efficacy of ferroptosis inducers." (PMID 36712673, 2022). "Notably, METTL3 enhances the development of lung adenocarcinoma, likely through the promotion of tumour occurrence and the inhibition of cell iron death by upregulating SLC7A11 expression." (PMID 39580709, 2024). "The histone deacetylase inhibitor vorinostat could promote ferroptosis in EGFR-mutant lung adenocarcinoma cells by inhibiting SLC7A11 (xCT) expression and enhancing the efficacy of ferroptosis inducers." (PMID 35151318, 2022). "It showed that SLC7A11 was up-regulated in patients or mice with lung adenocarcinoma We detected the correlation between the expression of miR-339 and SLC7A11 from the perspective of mRNA and protein, and found that miR-339 negatively regulates the expression of SLC7A11." (PMID 35399708, 2022). "Notably, genetic depletion or pharmacological inhibition of SLC7A11 induces synthetic lethality in KRAS-mutant lung adenocarcinoma, highlighting SLC7A11 as a potential therapeutic target for RAS-driven tumors." (PMID 36552652, 2022). "In addition, SLC7A11, a cystine/glutamate antiporter that specifically uptakes cystine, was overexpressed in patients with KRAS-mutated lung adenocarcinoma and positively associated with tumor progression." (PMID 34502181, 2021). "Additionally, CREB1 upregulates SLC7A11 expression in lung adenocarcinoma." (PMID 41228362, 2025). "We found a human-specific long non-coding RNA (lncRNA, ENST00000504300) induced by the inflammatory pathway, termed SLC7A11AR (SLC7A11 associated lncRNA), which was highly expressed in lung adenocarcinoma (LUAD) cell lines but not in lung squamous cell carcinoma (LUSC)." (PMID 40765833, 2025). "Indeed, oncogenic KRAS, closely related to lung adenocarcinoma development, induces an upregulation of the carrier SLC7A11 and, therefore, an increase in the intracellular concentration of cystine and cytoprotective glutathione in conditions of oxidative stress." (PMID 38539554, 2024). "However, there are few studies on whether SLC7A11 affects the immune status of lung adenocarcinoma (LUAD)." (PMID 37880315, 2023). "However, the mechanism of LncRNA in affecting the development of SLC7A11-mediated lung adenocarcinoma remains unclear." (PMID 35399708, 2022). "Therefore, we speculated that SLC7A11 may exert a carcinogenic effect in lung adenocarcinoma by inhibiting the death of tumor cells." (PMID 35399708, 2022). "Conversely, in hepatoblastoma and lung adenocarcinoma, METTL3 bolsters SLC7A11 mRNA stability, impeding ferroptosis." (PMID 40327848, 2025). "A recent study has discovered that the expression of the two components of xCT system, SLC3A2 and SLC7A11, can be modulated by proteins involved in m6A modification, YTHDC2 and METTL3, leading to the induction of ferroptosis in lung adenocarcinoma cells." (PMID 41339932, 2025). "Regarding the regulation of SLC7A11, METTL3 promotes lung adenocarcinoma (LUAD) tumor growth and inhibits ferroptosis by stabilizing the m6A modification of SLC7A11." (PMID 39800682, 2025). "In lung adenocarcinoma, YTHDC2 targets SLC3A2 and SLC7A11 in an RNA m6A-dependent manner, acting as an endogenous ferroptosis inducer." (PMID 40327848, 2025). "According to the findings, lung squamous cell carcinoma and lung adenocarcinoma cells have higher levels of RAC1, RPN1, and SLC7A11 mRNA than normal lung epithelial cells." (PMID 38968580, 2024). "SLC3A2 and SLC7A11 are two subunits of system XC−, and are the targets of the m6A reader YTHDC2 to execute ferroptosis in lung adenocarcinoma cells." (PMID 37714846, 2023).
lung adenocarcinoma (continued). "In patients with KRAS-mutant lung adenocarcinoma (LUAD), SLC7A11 mediates cystine uptake, decreases ROS production and thus promotes lung adenocarcinoma proliferation and migration." (PMID 38273826, 2023). "In lung adenocarcinoma, one study reported that the YTHDC2 m6A reader binds an SLC7A11 m6A site at the 3′UTR, leading to decreased mRNA stability and expression." (PMID 38023731, 2023). "In lung adenocarcinoma, YT521-B homology domain containing 2 (YTHDC2), which destabilises SLC7A11 mRNA and blocks the downstream antioxidant program in an m6A (N6-methyladenosine)-dependent manner, frequently suppresses tumourigenesis." (PMID 35804831, 2022). "In lung adenocarcinoma and hepatoblastoma, METTL3-mediated m6A modification could suppress ferroptosis and promote tumor progression by regulating SLC7A11 mRNA stability and translation." (PMID 40175350, 2025). "In addition, another novel SLC7A11 inhibitor, HG106, exhibited specific cytotoxicity against KRAS-mutant lung adenocarcinoma cells by inducing cell apoptosis through enhanced oxidative stress and ER stress pathways." (PMID 39569390, 2025). "The study showed that SLC7A11 is essential to elicit tumor formation and maintain tumorigenicity by relieving oxidative stress in COAD, pancreatic ductal adenocarcinoma (PDAC), and lung adenocarcinoma (LUAD)." (PMID 35517862, 2022). "Similarly, in a screen of mutant KRAS lung adenocarcinoma cells, HG106 was found to specifically inhibit SLC7A11 function and decrease tumor burden in vivo via ROS induction and mitochondrial and endoplasmic reticulum dysfunction." (PMID 35280777, 2022). "In addition, another study in lung adenocarcinoma (LUAD) demonstrated that METTL3 enhances RNA stability and promotes translation of SLC7A11 through m6A-mediated binding of YTHDF1 and YTHDC2, YTHDC2 prefers to bind to m6A-modified SLC7A11 mRNA and promoting its decay." (PMID 39799112, 2025). "However, their further investigations revealed that inhibition of SLC7A11 by YTHDC2 is not enough to induce ferroptosis in lung adenocarcinoma." (PMID 34926310, 2021).
liver cancer (50 papers, 2013 to 2025). An epithelial or non-epithelial malignant neoplasm that arises from the liver. "Patients with liver cancer showed high levels of immune cells associated with poor prognosis with SLC7A11." (PMID 38200525, 2024). "Here, we use comprehensive bioinformatics analyses and experimental validations to investigate SLC7A11's role in the liver cancer immune microenvironment, elucidate the underlying regulatory mechanisms, and offer insights on the RFA combination therapy model for HCC." (PMID 39742309, 2024). "Studies have found that the ferroptosis genes ABCB6, FLVCR1, SLC48A1, and SLC7A11 have excellent predictions through analysis, and M0 macrophages, follicular helper T cells (Tfh), memory B cells, and neutrophils account for a relatively large proportion of high-risk-score liver cancer patients." (PMID 38200525, 2024). "α-KG also downregulated SLC7A11, elevated oxidative stress, and induced DNA damage of liver cancer cells." (PMID 41321581, 2025). "Tumor heterogeneity leads to significant differences in the sensitivity of different cancer types to ferroptosis: gastric cancer is resistant due to low ACSL4 expression levels, while liver cancer is more sensitive due to high SLC7A11 expression levels." (PMID 40535125, 2025). "The SLC7A11 expression in normal adjacent tissues was ≤25%, indicating low expression, while that in liver cancer tissues was >25%, indicating high expression." (PMID 40978058, 2025). "In a recent preclinical study on liver cancer, researchers found that Mer proto-oncogene tyrosine kinase (MerTK) enhances SLC7A11 expression via the ERK/SP1 signaling pathway." (PMID 40012016, 2025). "Collectively, our data demonstrate that ZNF706 is a potential oncogene in liver cancer and functions as a ferroptosis regulator by modulating SLC7A11 expression, constituting a potential therapeutic target for HCC." (PMID 38862581, 2024). "Erastin is the most common inducer of ferroptosis in tumors, including melanoma, GC, lung cancer, and liver cancer, by inhibiting the expression of SLC7A11 to limit intracellular cysteine and glutathione levels." (PMID 38654314, 2024). "After RFA treatment in patients with liver cancer, the expression of SLC7A11/xCT and the proportion of DCs in the TME were significantly increased." (PMID 39742309, 2024). "To understand the role of SLC7A11 in DCs, we extracted normal tissues and tumor tissues from liver cancer patients in the GSE140228 single‐cell transcriptome and analyzed them." (PMID 39742309, 2024). "A large number of studies have shown that ncRNAs can affect the progression of liver cancer by mediating various ferroptosis-related classical molecules or signals, such as SLC7A11, GPX4, and ACSL4." (PMID 37065473, 2023). "The data revealed that the expression level of HAAO in liver cancer is negatively correlated with ferroptosis‐resistant genes including SLC7A11, SLC3A2, and ACSL3, whereas positively correlated with ferroptosis‐sensitive gene ACSL1." (PMID 36627132, 2023). "To verify the regulation of lncRNA HEPFAL on SLC7A11, we detected the expression levels of lncRNA HEPFAL and SLC7A11 in liver cancer cell lines." (PMID 36008384, 2022). "We provided the first evidence showing that C8orf76 was involved in ferroptosis regulation via transcriptional SLC7A11 activation to investigate the concrete mechanism of C8orf76 during liver cancer progression." (PMID 35884471, 2022). "This study reported that lncRNA HEPFAL, upstream of the key ferroptosis gene SLC7A11, regulates ferroptosis in liver cancer cells." (PMID 36008384, 2022). "In this study, we found that SLC7A11, an attracting oncogene and an indication of an unsatisfactory prognostic status of liver cancer, was significantly downregulated in EC." (PMID 34531924, 2021). "Therefore, we assessed the effect of Sorafenib, another SLC7A11-targeting ferroptosis inducer that has been used for liver cancer therapy in clinic, on Tamoxifen resistant ZR-75-1 cells in vitro and in vivo." (PMID 39833180, 2025).
liver cancer (continued). "SLC7A11/xCT is a poor prognostic marker for liver cancer and is mainly expressed in DCs in the TME." (PMID 39742309, 2024). "For example, some studies have shown that low expression of IFNγ manifests as a high metastasis rate and high recurrence rate of liver cancer, and activating CD8 + T cells to release IFNγ reduces the expression level of SLC7A11 and inhibits the cellular uptake of cystine, causing ferroptosis." (PMID 38200525, 2024). "Our conclusion is also consistent with these findings, as the characteristics of the sorafenib-resistant liver cancer cells used in our study, such as SLC7A11 expression, may have changed." (PMID 39507762, 2024). "In summary, lncRNA DUXAP8 may be used in combination with sorafenib to achieve a higher anti‐liver cancer efficacy by acting on the SLC7A11‐mediated ferroptosis pathway." (PMID 37337470, 2023). "Furthermore, the USP5‐mediated deubiquitination of LSH facilitates the tumorigenesis of HCC by upregulating solute carrier family 7 member 11 (SLC7A11) to suppress ferroptosis of liver cancer cells." (PMID 37492786, 2023). "In liver cancer, Erianin induces ferroptosis by activating JAK2/STAT3 and inhibiting SLC7A11 and GPX4 expression, reducing HCC cell proliferation and invasion." (PMID 40994946, 2025). "Western blot results showed that the expression levels of GPX4 and SLC7A11 in the CK + AS1842856 group were increased compared with the CK group, indicating that CK induced ferroptosis in liver cancer cells through FOXO signaling pathway." (PMID 38664638, 2024). "More importantly, in the present study, the single-cell sequencing analysis results implied that SLC7A11, SLC1A5, CARS1, RPL8 and TFRC were not only upregulated in liver cancer cells but also expressed in immune cells." (PMID 35847985, 2022). "In contrast, in liver cancer, USP5 stabilizes SLC7A11 through deubiquitination." (PMID 41213937, 2025). "Several studies have shown that HSPA8 inhibits ferroptosis by promoting SLC7A11/GSH/GPX4 signalling and inhibiting NCOA4-mediated ferritinophagy, We verified the effects of HSPA8 in liver cancer and found that LACTB promotes ferroptosis by regulating HSPA8-mediated ferroptosis-related signalling." (PMID 39047638, 2024). "The role of SLC7A11 on autophagy has been previously reported, whereby dysregulated SLC7A11 expression inhibited cell growth through the ROS/autophagy pathway in liver cancer, but there is no prior evidence of the gene acting as a ceRNA." (PMID 34790572, 2021). "The liver cancer cell line data from the CTRP revealed a significant correlation between LIFR expression and the sensitivity to erastin, which targets the cystine transporter SLC7A11 to induce ferroptosis." (PMID 34921145, 2021). "However, in the results of the local scan analysis, SLC7A11 did not exhibit this differential expression between all liver cancer and healthy individuals." (PMID 40007539, 2025). "Unlike the mechanism in liver cancer, where circPIAS1 inhibits ferroptosis through the miR-455-3p/NUPR1 axis, YBX3 directly targets SLC7A11 and destabilizes it through lysosomal degradation." (PMID 41213937, 2025).